ANXA5 (annexin A5)
Diseases named in the same sentence as ANXA5 in open-access papers (continued):
Sharing a sentence is not in itself a finding about the gene and the disease.
Tricuspid regurgitation (1 paper, 2012). Failure of the tricuspid valve to close sufficiently upon contraction of the right ventricle, causing blood to regurgitate (flow backward) into the right atrium. "Among patients, plasma AnxA5 correlated significantly with subpulmonary LV eccentricity index (r = 0.43, p = 0.027), with the correlation remaining the same even with exclusion of the one patient with severe tricuspid regurgitation." (PMID 23284897, 2012).
ulcerative colitis (1 paper, 2025). An inflammatory bowel disease involving the mucosal surface of the large intestine and rectum. "For example, both NR4A1 and ANXA5 were associated with ulcerative colitis (UC); NR4A1 expressed in intestine tissues, inflammatory cells and epithelium, regulated the differentiation and function of Paneth cell; ANXA5 had differential expression in the jejunal mucosa of IUGR and normal piglets." (PMID 41190166, 2025).
tumor (681 papers, 2001 to 2026). "Research has found that ANXA5 is associated with tumor-associated macrophages and has preliminarily verified through immunohistochemistry and angiogenesis experiments that ANXA5 has the role of predicting the survival time of GC patients." (PMID 40124374, 2025). "For instance, bacterial L-methionase, which catalyzes the degradation of the essential amino acid L-methionine, was linked to AnxA5 to target it specifically to tumor cells." (PMID 38573347, 2024). "Annexin A5 upregulation was found to be associated with advanced tumor stage, increased recurrence and lower OS in CRC." (PMID 28423508, 2017). "Furthermore, we demonstrated that AnxA5 can also serve as a homing molecule to concentrate AnxA5-linked tumor-antigens into PS-rich TME to enhance the magnitude of localized antitumor immunity." (PMID 32111835, 2020). "Tumor uptake of fluorescent annexin A5-variants was measured using non-invasive optical imaging." (PMID 24801051, 2014). "Analysis of surgical samples indicated that the expressing levels of KLF2 and ANXA5 were associated with infiltrating immune cells and the expression of PD-L1 at the immune checkpoint in tumor tissues Our analysis showed that immune microenvironment and tumor immunity serve a crucial part in HCC." (PMID 35992798, 2022). "The small animal live imaging found that the knockdown of ANXA5 significantly inhibited tumor growth in vivo." (PMID 40607003, 2025). "This study estimated the tumor-promoting role of ANXA5 in transfected U251 and SHG44 cells and also elucidated its underlying mechanism." (PMID 40607003, 2025). "In tumor cells, ANXA5 enables dendritic cells to regain their capacity for antigen presentation to CD8+ T cells by blocking PS exposure on tumor cells." (PMID 40342928, 2025). "A summary of the more relevant functions and corresponding signaling pathways (or related molecular mechanism) of ANXA5 in normal tissue and tumor cells is presented below, followed by a detailed account." (PMID 40342928, 2025). "The efficacy of re-activating the immune system with AnxA5-dependent delivery of tumor antigens was further enhanced by ICB." (PMID 38573347, 2024). "Our analysis of BLCA patient tissues and cell lines using PCR techniques reveals overexpression of ANXA5 within both tumour tissues and cells." (PMID 39400959, 2024). "Direct anti-tumor effects and the improvement of survival have been observed with systemic Annexin A5 at higher doses in several cancer in vivo models." (PMID 39204083, 2024). "There was a clear inhibitory effect on tumor angiogenesis, and Annexin A5 was demonstrated to inhibit the secretion of VEGF in vivo." (PMID 39204083, 2024). "We have recently reported that two different PS-binding proteins, annexin A5 and a carboxylated glutamic acid domain of Protein S (GlaS), bound EVs isolated from murine tumor cells." (PMID 36992223, 2023). "Fusion of ANXA5 with antigenic peptides of tumor cells not only concentrates tumor antigen peptides in TME but also exaggerates the effects of other immune checkpoint inhibitors." (PMID 36611989, 2023). "ANXA5 is one of the most common proteins that is overexpressed in a series of cancers and participates in the multi-step process of tumor development." (PMID 37759912, 2023). "Annexin A5 was found to interact with polycystin-1, a metastasis-related protein that induces the suppression of tumor metastasis." (PMID 37242681, 2023). "The level of ANXA5 correlates with in vitro and in vivo tumor aggressiveness and lymphatic metastasis in mouse hepatocarcinoma cells." (PMID 36983670, 2023). "The contribution of NUCB1 and ANXA5 in tumor progression and drug responses in DLBCL remains controversial, so revealing their exact roles in DLBCL behavior and prognosis needs further investigation." (PMID 36611989, 2023). "We have previously demonstrated that fluorescently labeled GlaS and annexin A5 proteins can bind EVs derived from tumor cells." (PMID 36992223, 2023).
tumor (continued). "The level of ANXA5 appears to be higher in treated tumor cells than in untreated cells, but the level of ANXA5 in resistant DLBCL tumor cells requires further investigation." (PMID 36611989, 2023). "Anxa5 is up-regulated in several tumors and is involved in tumor progression, invasion, metastasis, and drug resistance." (PMID 36362243, 2022). "No significant ACI differences were observed for α-SMA or CK-19 levels in these groups, indicating a possible correlation between annexin A5 and patient tumor responses." (PMID 36282600, 2022). "ANXA5 acts as a tumor-targeting protein and reduces the amount of SWCNTs required to eradicate the primary tumor." (PMID 35808119, 2022). "ANXA5 is considered a predictive biomarker for tumor development, progression, invasion, and metastasis, and is suggested to be of diagnostic, prognostic, and therapeutic importance in cancer." (PMID 35884419, 2022). "We retrospectively quantified apoptotic responses and tumor-stroma cell proportions in PDOs via 3D immunofluorescence imaging through annexin A5, α-smooth muscle actin (α-SMA), and cytokeratin 19 (CK-19) levels." (PMID 36282600, 2022). "In hepatocarcinoma, AnxA5 overexpression promoted in vivo tumour malignancy and lymphatic metastasis, most likely through MAPK and Rac1 signaling pathways." (PMID 33810523, 2021). "The SWCNTs were functionalized with the protein annexin A5 (ANXA5), which has great affinity to the anionic phospholipid phosphatidylserine expressed on endothelial cells of the tumor vasculature and on tumor cell membranes." (PMID 34835896, 2021). "Prior to photothermal therapy, the SWCNT-ANXA5 bioconjugate was administered systemically at a relatively low dose of 1.2 mg/kg, where it then accumulated in tumor vasculature via ANXA5-dependent binding." (PMID 33411055, 2021). "Drug-induced apoptosis in tumour-bearing mice was also detectable using AnxA5-conjugated ultrasmall superparamagnetic iron oxide." (PMID 33810523, 2021). "A novel AnxA5-conjugated nano-sized ultrasound contrast agent was able to detect apoptotic cells inside tumours after chemotherapy." (PMID 33810523, 2021). "The use of the tumor vascular targeting protein ANXA5 minimized the amount of systemically delivered SWCNT necessary to eradicate primary tumors in a low one-time dose." (PMID 33411055, 2021). "Magnetic beads coated with AnxA5 were recently used to isolate tumour-derived extracellular vesicles from mouse models xenografted with human cancer cells, an approach with diagnostic and therapeutic potential." (PMID 33810523, 2021). "With the high affinity for PS, ANXA5 can bind to aged erythrocytes, activated platelets, endothelial microparticles, and tumor vascular, for the exposed PS on their surfaces." (PMID 34131110, 2021). "Due to the preferential homing of AnxA5 to the TME enriched with PS+ tumor cells, we demonstrate in vivo that fusing tumor-antigen peptide to AnxA5 significantly enhances its immunogenicity and antitumor efficacy when administered after chemotherapy." (PMID 32111835, 2020). "In support of this result, ANXA5 shows tumor promoter activity in the majority of many kinds of tumor, including HCC." (PMID 32904199, 2020). "Due to the high affinity binding between AnxA5 and PS exposed on the surface of apoptotic and tumor cells, AnxA5 has been shown to possess tumor homing capabilities, and has been utilized as guiding and labeling tools for imaging tumor cell apoptosis." (PMID 32111835, 2020). "We thus reasoned that AnxA5 can serve not only as an immune checkpoint inhibitor for tumor treatment, but also as a potent guiding molecule to home vaccine incorporated tumor antigens to the tumor." (PMID 32111835, 2020). "The reduction in immunosuppressive MDSC and Treg populations was also observed in the spleens of tumor-bearing mice following cisplatin and AnxA5 treatment." (PMID 32111835, 2020).
tumor (continued). "Following TC-1 tumor challenge, cisplatin treatment, and/or AnxA5 administration, we harvested the tumor tissues from tumor-bearing mice and assessed the presence of various immune cell populations and cytokines within the TME." (PMID 32111835, 2020). "Concurrent administration of cisplatin, E7 long peptide, and AnxA5 resulted in potent control of TC-1 tumor growth compared to other treatments." (PMID 32111835, 2020). "We sought to evaluate the applicability of AnxA5-antigenic peptide fusion protein as a treatment strategy following a different chemotherapeutic agent, as well as against a different tumor model." (PMID 32111835, 2020). "Particularly, we showed that systemic administration of AnxA5 following chemotherapy can enhance the immunogenicity of local tumor antigens." (PMID 32111835, 2020). "The levels of CRKI/II and RAC1 were reduced in tumor tissues from mice transplanted with Hca-P cells with stable ANXA5 knockdown." (PMID 29802377, 2018). "Conclusively, ANXA5 downregulation inhibited hepatocarcinoma cell induced primary tumor growth of mice via downregulating CRKI/II and RAC1." (PMID 29802377, 2018). "Similar result was obtained on the influence of ANXA5 knockdown on VEGF-3 expression in primary tumor induced by Hca-P cell transplantation in mouse." (PMID 29802377, 2018). "97, 108, 109 The fact that AnxA5 has been shown to serve as an adjuvant for apoptotic tumor cells by blocking PS-dependent signals in phagocytes, supports the further development of annexin proteins as PS antagonists." (PMID 26915293, 2016). "We provided evidence that up-regulation of ANXA5 activated the glycolysis and gluconeogenesis of tumor cells." (PMID 27684953, 2016). "It is worth noting that a big proportion of the proteins affected by ANXA5 are involved in cellular catabolism and metabolism, which is a key step in tumorigenesis and tumor progression." (PMID 27684953, 2016). "Pre-clinical experiments revealed a long-lasting immune memory against tumor cells and a delayed tumor growth mediated by AnxA5 when given in combination with IR." (PMID 26500646, 2015). "Then, in the final wider application, the HFs of [18F]FDG and AnxA5 in four tumour-bearing animals were calculated for different post-scan processing parameters." (PMID 26501820, 2015). "In this analysis, we compared the heterogeneity of the uptake of two tracers, [18F]FDG and AnxA5, in the same tumour, i.e. same day, same animal, same tumour, but different tracers of different size and retention mechanisms." (PMID 26501820, 2015). "In the two images through one plane (b or, alternatively) the uptake of mTrx-GFP appeared varied and patchy while that of AnxA5 was more uniformly distributed throughout the tumour." (PMID 26501820, 2015). "In this paper we investigated effects of increasing size of anxA5 on PS-targeting to a tumor in a cyclophosphamide (CYP) treated HT29 human colon carcinoma xenograft mouse model using non-invasive optical imaging." (PMID 24801051, 2014). "In order to study effect of increasing size of anxA5 on dynamics of tumor uptake we conducted non-invasive molecular imaging using the well-vascularized HT29 tumor model in NMRI nude mice." (PMID 24801051, 2014). "AnxA5 has been coupled to polyethylene glycol and nanostructures to prolong circulation time and to improve tumor uptake." (PMID 24801051, 2014). "AnxA5-NP and M1234-NP also accumulated in tumor, albeit with kinetics and at levels different from those of the monomers." (PMID 24801051, 2014). "In order to prolong circulation time and, consequently, tumor uptake, the size of anxA5 was increased by biotinylation and subsequently complexation with streptavidin." (PMID 24801051, 2014). "Increasing annexin A5 size prolongs circulation times and increases tumor uptake, but decreases contribution of PS-targeting to tumor uptake and abolishes power to report efficacy of therapy." (PMID 24801051, 2014).
tumor (continued). "AnxA5 uptake exceeded always M1234 uptake indicating that PS-binding contributed to anxA5 accumulation in the tumor." (PMID 24801051, 2014). "AnxA5 accumulated more than M1234 and its tumor level increased by CYP-treatment during the time-course in contrast to M1234, the uptake of which showed a decrease in response to CYP-treatment." (PMID 24801051, 2014). "As PS is expressed on stressed and dying cells, AnxA5 is currently a promising vector for tumour imaging and targeted drug delivery in oncology as well as for the visualization of vulnerable plaques in patients (for review see 8,9,21)." (PMID 25214012, 2014). "Cell death of a tumor is regarded amongst the most promising targets and anxA5, which binds dying and dead cells, is appreciated as the most promising Molecular Imaging-agent." (PMID 24801051, 2014). "Others reported optimal imaging time-points between 4 and 6 hours post-injection based on tumor-blood ratios of labeled anxA5." (PMID 24801051, 2014). "Tumor uptake of annexin A5-streptavidin was higher and persisted longer than annexin A5-uptake but depended less on phosphatidylserine binding." (PMID 24801051, 2014). "Altogether our results demonstrate that increasing size of anxA5 to ±200 kDa reduces contribution of PS-binding to uptake in the HT29-tumor model due to EPR effects." (PMID 24801051, 2014). "Increasing size of anxA5 above this threshold would, hence, change maximal tumor uptake, time-course of uptake and contribution of target affinity to uptake." (PMID 24801051, 2014). "CYP-treatment caused an increase of cell death in the tumor explaining the higher uptake of anxA5 by CYP-treated tumor." (PMID 24801051, 2014). "Estimation of the intra-, inter-, and day-to-day reproducibility of quantitative 99mTc-HYNIC-Annexin A5 tumor uptake values." (PMID 24216991, 2013). "Quantitative 99mTc-HYNIC-Annexin A5 tumor uptake correlated well with the number of apoptotic cells if only tumor samples with no or minimal amounts of necrosis were considered." (PMID 24216991, 2013). "Both visual (r = 0.97, p < 0.0001) and quantitative (r = 0.99, p < 0.0001) analysis of 99mTc-HYNIC-Annexin A5 tumor uptake significantly correlated with TRR." (PMID 24216991, 2013). "The authors conclude that “the reproducibility of quantitative 99mTc-HYNIC-Annexin A5 tumor uptake measurement using a manual method appears to be acceptable for clinical use”." (PMID 24216991, 2013). "In 2006, Rottey and colleagues studied the changes in 99mTc-HYNIC-Annexin A5 tumor uptake after chemotherapy in a variety of patients." (PMID 24216991, 2013). "In 2004, the same group published a paper estimating the intra-, inter-, and day-to-day reproducibility of manually defined quantitative 99mTc-HYNIC-Annexin A5 tumor uptake values in 11 HNC patients." (PMID 24216991, 2013). "Identifying the relationship between baseline quantitative 99mTc-HYNIC-Annexin A5 tumor uptake and the number of apoptotic cells derived from histologic analysis after surgical resection." (PMID 24216991, 2013). "Successful anti-cancer treatment is expected to have a high apoptosis inducing potential and should thus reflect in increased 99mTc-HYNIC-Annexin A5 tumor uptake ASOT compared to baseline." (PMID 24216991, 2013). "Identifying the reliability of visual analysis of 99mTc-HYNIC-Annexin A5 tumor uptake compared to quantitative tracer uptake evaluation." (PMID 24216991, 2013). "The accumulation of 99mTc-HYNIC-annexin A5 in tumor tissue was also significantly higher than in that of the untreated group." (PMID 24324676, 2013). "A highly significant correlation (r2 = 0.86, p < 0.0001) was found, indicating an increased tumor uptake of 99mTc-HYNIC-Annexin A5 ASOT to be a potential predictor of clinical therapy outcome." (PMID 24216991, 2013). "Both visual (r = 0.97, p < 0.0001) and quantitative (r = 0.99, p < 0.0001) analysis of 99mTc-HYNIC-Annexin A5 tumor uptake correlated significant with TRR." (PMID 24216991, 2013).